ANXA6 (annexin A6)
Description:
May associate with CD21. May regulate the release of Ca(2+) from intracellular stores.
Synonyms: CPB-II; ANX6; CBP68; p68; p70
Tractability: Small molecule: it has a high-quality binding pocket. Antibody: its Gene Ontology location is reachable by antibodies, with medium confidence. PROTAC: ubiquitination databases record sites on it; its protein half-life has been measured.
Target class: Ion channel; Annexin; Other ion channel
Gene: Protein-coding gene on chromosome 5 (151,100,706 to 151,157,815, reverse strand). Ensembl gene ENSG00000197043.
Subcellular location: Cytoplasm; Melanosome
Subcellular location (Human Protein Atlas): Cytosol; Basal body
Pathways (Reactome):
Muscle contraction: Smooth Muscle Contraction
Gene Ontology:
Molecular function: calcium-dependent phospholipid binding; calcium-dependent protein binding; cholesterol binding; GTP binding; identical protein binding; ligand-gated monoatomic ion channel activity; lipid binding; protein binding; phosphatidylserine binding; calcium ion binding
Biological process: monoatomic ion transmembrane transport; apoptotic signaling pathway; calcium ion transport; mitochondrial calcium ion homeostasis
Cellular component: extracellular exosome; extracellular matrix; focal adhesion; late endosome membrane; lysosomal membrane; membrane; nucleus; plasma membrane; vesicle membrane; cytoplasm; melanosome; mitochondrion
Genetic constraint (gnomAD): Loss-of-function variants: 61 observed, 86.62 expected, observed/expected ratio (o/e) 0.7, 90% interval 0.57 to 0.87. The upper end of that interval is the gene's LOEUF score, 0.87, which puts it in group 3 of 6, group 1 being the genes least tolerant of losing a copy. Missense variants: 813 observed, 866 expected, observed/expected ratio (o/e) 0.94, 90% interval 0.88 to 1. Synonymous variants: 287 observed, 317.5 expected, observed/expected ratio (o/e) 0.9, 90% interval 0.82 to 1.
Homologues: Orthologues: chimpanzee ANXA6 (99% identical), macaque ANXA6 (99% identical), dog ANXA6 (96% identical), rat Anxa6 (95% identical), mouse Anxa6 (94% identical), pig ANXA6 (94% identical), guinea pig ANXA6 (93% identical), rabbit ANXA6 (80% identical), tropical clawed frog anxa6 (77% identical), zebrafish anxa6 (60% identical), Drosophila melanogaster AnxB9 (22% identical), Drosophila melanogaster AnxB11 (20% identical). Paralogues in human: ANXA11 (28% identical), ANXA5 (27% identical), ANXA4 (26% identical), ANXA8 (25% identical), ANXA8L1 (25% identical), ANXA3 (24% identical), ANXA2 (23% identical), ANXA7 (22% identical), ANXA1 (22% identical), ANXA13 (21% identical), ANXA10 (20% identical), ANXA9 (17% identical).
Diseases named in the same sentence as ANXA6 in open-access papers:
ANXA6 is named in the same sentence as 118 diseases in open-access papers, as found by Europe PMC text mining. Sharing a sentence is not in itself a finding about the gene and the disease. The quoted sentences say what the papers report.
breast carcinoma (41 papers, 2007 to 2026). "In particular, exosome-derived ANXA6 from breast cancer stem cells and pancreatic-cancer-associated fibroblasts promotes more aggressive tumour growth in vivo." (PMID 36765657, 2023). "The expression levels of AnxA6 are closely associated with melanoma, cervical cancer, epithelial carcinoma, breast cancer, gastric cancer, prostate cancer, acute lymphoblastic leukemia, chronic myeloid leukemia, large-cell lymphoma, and myeloma." (PMID 37528485, 2023). "Low ANXA6 expression was also significantly associated with suppressed tumor activity and the survival of patients with basal-like breast cancer." (PMID 37129645, 2023). "Compared to the EV control cells, the overexpression of AnxA6 in this basal-like breast cancer cell line was associated with higher OCR and ECAR, as well as significantly higher proton leak (p = 0.0361) and ATP production (p = 0.0284)." (PMID 35267416, 2022). "In basal-like breast cancer, reduced ANXA6 expression was significantly associated with higher recurrence-free but lower distant metastasis-free and overall survival." (PMID 36247003, 2022). "This analysis also revealed that the expression of low AnxA6/high GRF2 and high Ki67 is associated with poorer RFS of basal-like breast cancer patients compared to those expressing high AnxA6/low GRF2 and low Ki67." (PMID 32298357, 2020). "These include the findings that AnxA6-enriched EVs from cancer-associated fibroblasts elicited proinvasive properties when taken up by pancreatic and breast cancer cells." (PMID 32784650, 2020). "We previously reported that high AnxA6 and low RasGRF2 expression is associated with poorer distant relapse-free survival of basal-like breast cancer patients compared to patients with low AnxA6 and high GRF2 expressing basal-like breast cancer." (PMID 32298357, 2020). "The role of AnxA6 in breast cancer and in particular, the mechanisms underlying its contribution to tumor cell growth and/or motility remain poorly understood." (PMID 30719209, 2019). "Breast cancer cells secrete annexins, including annexin A6, which are predominantly cell surface-associated via the exosomal pathway." (PMID 29462943, 2018). "AnxA1, AnxA2, and AnxA6 were the only annexins identified to be significantly associated with clinical outcomes of TNBC patients in comparison with all other breast cancer subtypes." (PMID 29416802, 2018). "This study demonstrates that the enhanced degradation of activated EGFR in AnxA6-depleted invasive breast cancer cells underlies their sensitivity to EGFR-targeted TKIs and attenuated motility." (PMID 24354805, 2013). "We also provide evidence suggesting that reduced AnxA6 expression is associated with a better relapse-free survival but poorer distant metastasis-free and overall survival of basal-like breast cancer patients." (PMID 24354805, 2013). "Low AnxA6 expression is associated with a significantly higher RFS for patients with basal-like breast cancer (p = 0.023)." (PMID 24354805, 2013). "We also show that low AnxA6 expression is associated with a better relapse-free survival but poorer overall and distant metastasis-free survival of basal-like breast cancer patients." (PMID 24354805, 2013). "Moreover, AnxA6-enriched EVs from cancer-associated fibroblasts elicited proinvasive properties when taken up by breast cancer cells." (PMID 34073560, 2021). "However, AnxA6 expression status is significantly associated with the survival of patients with basal-like breast cancer." (PMID 24354805, 2013). "Given that AnxA6 expression is lower in breast cancer, it was necessary to assess whether AnxA6 expression status is associated with patient outcome." (PMID 24354805, 2013). "Previous studies predominantly delved into the mechanistic roles of sEV cargo, including ANXA6, miR-378a-3p, miR-378d, circBACH1, primarily within the context of breast cancer." (PMID 38362150, 2024).
breast carcinoma (continued). "ANXA6-EVs induced by continuous chemotherapeutic pressure promotes drug resistance, cell migration, stemness, and autophagy in paclitaxel-sensitive breast cancer cells." (PMID 37129645, 2023). "ANXA6 knockdown in breast cancer cells (MDA-MB-436) increased Ras activity and cell proliferation in anchored growth assay." (PMID 37129645, 2023). "We showed recently that ANXA5 and ANXA6 silencing prevents metastasis of breast cancer cells in vivo." (PMID 38092984, 2023). "Coincidentally, the silencing of ANXA6 leads to the death of migrating breast cancer cells (MDA-MB-231) due to the double-sided nature of membrane repair mechanisms." (PMID 37129645, 2023). "Reduced ANXA6 expression was found in breast cancer tissues, but elevated in invasive breast cancer phenotypes." (PMID 37129645, 2023). "On the other hand, tumor promoter activities of AnxA6 have also been reported, with AnxA6 displaying pro-invasive functions in invasive breast cancer cells." (PMID 35806209, 2022). "In breast cancer, ANXA6 present in exosomes from stem cells promoted paclitaxel resistance via YAP1 upregulation." (PMID 36247003, 2022). "ANXA6 is highly expressed in a variety of tumours, such as acute myeloid leukaemia, bladder cancer, and breast carcinoma." (PMID 39290334, 2022). "Previous studies have reported the involvement of ANXA6 in both the positive and negative regulation of breast cancer cell growth, proliferation, and invasion." (PMID 34238922, 2021). "In a different study, the number of EVs significantly increased in breast cancer cells exposed to paclitaxel and doxorubicin and also became enriched with the cell signaling protein annexin 6 (ANXA6) that enhanced premetastatic capacity in vitro." (PMID 34337063, 2021). "The identification of a monoclonal AnxA6 antibody with anti-invasive properties on aggressive pancreatic, lung squamous and breast cancer cells further supports pro-metastatic activity of extracellular AnxA6." (PMID 33810523, 2021). "AnxA2 and AnxA6, expressed on the cell surface, were shown to serve as receptors for adhesion to immobilized FetuA in breast carcinoma cells." (PMID 33924370, 2021). "These anti-invasive activities of AnxA6 in A431 cells are, however, opposite to the proinvasive effects of AnxA6 in several other cancer cell types including invasive breast cancer cells, and migratory neural crest cells." (PMID 32784650, 2020). "It is increasingly becoming clear that the AnxA6 expression status varies greatly in breast cancer cells as tumor cells with mesenchymal-like phenotypes express higher levels of the protein compared to those with basal-like morphology." (PMID 32784650, 2020). "Several studies have shown that the calcium dependent membrane binding Annexin A6 (AnxA6) is downregulated in malignant forms of breast cancer, gastric cancer melanomas, esophageal adenocarcinoma and several other solid tumors." (PMID 32298357, 2020). "In breast cancer, reduced expression of AnxA6 and its tumor suppressor function is more relevant in TNBC than in non-TNBC subtypes, an observation that is consistent with the differences in the malignancy of these breast tumors." (PMID 32784650, 2020). "These molecular features appear to be critical in the multiple functions of AnxA6 in various cell types and pathological conditions including breast cancer." (PMID 32784650, 2020). "However, our data suggesting that low AnxA6 and high GRF2 expression levels are associated with poorer RFS of basal-like breast cancer patients compared to high AnxA6 and low GRF2 expression levels led us to speculate that the ratio of GRF2 to AnxA6 can delineate rapidly growing from invasive TNBCs." (PMID 32298357, 2020). "In breast cancer, the low AnxA6 expression levels in the more aggressive basal-like triple-negative breast cancer (TNBC) subtype correlate with its tumor suppressor activity and the poor overall survival of basal-like TNBC patients." (PMID 32784650, 2020).
breast carcinoma (continued). "Meanwhile, some studies have shown that AnxA6 is downregulated in the highly malignant forms of gastric cancer, hepatocellular carcinomas, cervical cancer and breast cancer." (PMID 32784650, 2020). "Although AnxA6 has been demonstrated to be a tumor suppressor in several tumor types, evidence supporting its role in breast cancer has thus far remained indirect." (PMID 30719209, 2019). "In this study, we demonstrate that loss of AnxA6 in TNBC cells is associated with early onset and rapid growth of xenograft tumors in mice, thus supporting its role as a tumor suppressor in breast cancer." (PMID 30719209, 2019). "Throughout the years of investigation Annexin A1 (AnxA1), Annexin A2 (AnxA2), Annexin A3 (AnxA3), Annexin A4 (AnxA4), Annexin A5 (AnxA5), Annexin A6 (AnxA6), and Annexin A8 (AnxA8) have all been identified as potential modulators of breast cancer progression." (PMID 29416802, 2018). "In malignancies, ANXA6 has been reported to play a role as a tumor suppressor in melanoma, breast cancer and gastric cancer." (PMID 29849941, 2018). "Knocking down annexin A6 in invasive BT-549 breast cancer cells was accompanied by enhanced anchorage-independent cell growth, but cell–cell cohesion, cell motility, and invasiveness were strongly inhibited." (PMID 29462943, 2018). "Further studies are warranted to provide a rationale for the use of AnxA6 expression status as a predictive marker for basal-like breast cancer and to identify patients with this breast cancer subtype who are more likely to respond to EGFR-targeted therapies." (PMID 24354805, 2013). "This notion is supported by the rapid degradation of activated EGFR, loss of invasiveness and sensitivity to EGFR-targeted TKIs following down regulation of AnxA6 in invasive breast cancer cells." (PMID 24354805, 2013). "Given the heterogeneity of breast cancer cells, it is plausible to suggest that the different outcomes of AnxA6 modulation of EGFR in MDA-MB-231 cells and BT-549 cells are cell type specific and presumably dictated by the level of AnxA6 expression." (PMID 24354805, 2013). "High AnxA6 levels were on the other hand, are associated with higher OS (p = 0.0024) and DMFS (p = 0.019) for patients with this breast cancer subtype." (PMID 24354805, 2013). "The growing evidence that AnxA6 expression promotes cell migration but attenuates cell proliferation implies that this tumor suppressor plays an important role in breast cancer progression and/or patient survival." (PMID 24354805, 2013). "The association of AnxA6 expression status with the survival of patients with this breast cancer subtype is consistent with the modulation of the stability of activated EGFR in invasive breast cancer cells by AnxA6." (PMID 24354805, 2013). "The present studies suggest important roles for AnxA2 and AnxA6 in exosomal mediated adhesion with implications in the progression of breast cancer." (PMID 21915303, 2011). "Similarly, the lungs are also home to EVs originating from breast cancer that include ANXA6, which is released in response to chemotherapy." (PMID 40574836, 2025). "Similarly, in breast cancer, chemotherapy stress can stimulate tumor cells to shed EVs enriched in annexin A6 (ANXA6)." (PMID 40574836, 2025). "SFXN3 and ANXA6 had also been reported to be over-expressed in breast cancer." (PMID 39844043, 2025). "Moreover, ANXA6 is differentially expressed in melanoma, cervical cancer, epithelial cancer, breast cancer, gastric cancer, and other tumors." (PMID 37129645, 2023). "The mechanism of ANXA6 has been extensively studied in breast cancer." (PMID 37129645, 2023). "ANXA6 expression of breast cancer appears to be complex and multifunctional." (PMID 37129645, 2023). "However, AnxA6 acts as a promoting factor in invasiveness of breast cancer and acute lymphoblastic leukemia." (PMID 37528485, 2023).
breast carcinoma (continued). "Silencing of ANXA6 in invasive BT-549 breast cancer cells could enhance the anchor cell growth, but with strong inhibition of intercellular cohesion, cell adhesion/diffusion, cell motility, and invasiveness." (PMID 37129645, 2023). "In addition to paclitaxel, adriamycin also promoted the entry of ANXA6 into exosomes and facilitated lung metastasis of breast cancer." (PMID 35719975, 2022). "Also, earlier reports linked extracellular AnxA6 with adhesive properties of metastatic cells and exosomal AnxA6 influenced BT-549 breast cancer cell motility, FA (dis-) assembly and FAK signalling." (PMID 35022465, 2022). "ANXA6 was also found necessary for an efficient motility and invasion of breast cancer cells." (PMID 36247003, 2022). "In order to verify the effect of ANXA6, the researchers knocked out the ANXA6 gene in breast cancer cells and found that exosomes secreted by paclitaxel-induced cancer cells did not carry ANXA6 and no longer had the function of promoting lung metastasis of tumor." (PMID 35719975, 2022). "Another study from the same group showed that ANXA6 could also promote resistance to some EGFR-TKIs in breast cancer cells." (PMID 36247003, 2022). "The authors claimed that detection of AnxA6 might not only be useful as a potential biomarker for specific breast cancer subtypes but might also be a promising predictor of especially basal-like TNBC to targeted therapeutic interventions." (PMID 34073560, 2021). "This suggests that differential expression of AnxA6 may be useful for the prediction of not only the survival, but also the likelihood of basal-like breast cancer patients to respond to EGFR-targeted therapies." (PMID 32784650, 2020). "This suggests that AnxA6 levels in EVs from molecularly distinct breast cancer subtypes and/or chemotherapy-treated patients may be useful to predict the risk of metastasis especially in patients who do not achieve a complete pathological response." (PMID 32784650, 2020). "Interestingly, AnxA6 expression levels are relatively lower in the more aggressive basal-like breast cancer TNBC cell lines than in the more invasive mesenchymal-like TNBC cell lines." (PMID 32784650, 2020). "To accomplish this, we stained normal and breast disease tissues in a TMA that included non-malignant fibroadenomas and hyperplasia, malignant mostly carcinomas, inflammation, and metastatic breast cancer tissues with antibodies against AnxA6, GRF2, SOS1 and Ki67." (PMID 32298357, 2020). "The proinvasive activity of AnxA6 is further reinforced by the identification of a monoclonal antibody (9E1) against AnxA6 with anti-invasive properties on several aggressive cancer cells including pancreatic, lung squamous and breast cancer cells." (PMID 32784650, 2020). "Annexin A6 promotes invasiveness and motility of breast cancer cells." (PMID 31803605, 2019). "AnxA6 expression is reduced in breast cancer cells and when expressed terminates EGFR signaling." (PMID 29416802, 2018). "The poorer distant metastasis-free and overall survival of patients with low AnxA6-expressing basal-like breast cancers could be attributed to the potentially more aggressive growth of the tumors and/or secondary lesions." (PMID 24354805, 2013). "On the other hand, and as demonstrated in this study, the better recurrence-free survival of low AnxA6-expressing basal-like breast cancer patients may be due to the their greater probability to respond to targeted therapy." (PMID 24354805, 2013). "Pending validation, patients with the more aggressive basal-like breast cancers in which AnxA6 expression is low may be more likely to respond to some EGFR-targeted therapies." (PMID 24354805, 2013). "We therefore, investigated the contribution of AnxA6 in the activity of EGFR in invasive breast cancer cells and examined whether the expression status of AnxA6 influences the response of these cells to EGFR-targeted TKIs and/or patient survival." (PMID 24354805, 2013).